CYCSP52 (CYCS pseudogene 52)
Synonyms: HCP2; HC6
Gene: Processed pseudogene on chromosome 1 (157,128,362 to 157,128,671, forward strand). Ensembl gene ENSG00000235700.
Diseases named in the same sentence as CYCSP52 in open-access papers:
CYCSP52 is named in the same sentence as 5 diseases in open-access papers, as found by Europe PMC text mining. Sharing a sentence is not in itself a finding about the gene and the disease.
CYCSP52 shares sentences with these, for which no sentence is quoted: infection (3 papers); meningitis (3); bacterial infection (1); cholera (1); Sepsis (1).